TRPT1 (tRNA phosphotransferase 1)
Description:
Catalyzes the last step of tRNA splicing, the transfer of the splice junction 2'-phosphate from ligated tRNA to NAD to produce ADP-ribose 1''-2'' cyclic phosphate.
Synonyms: MGC11134
Tractability: Small molecule: a structure with a bound ligand is known. PROTAC: ubiquitination databases record sites on it; its protein half-life has been measured.
Gene: Protein-coding gene on chromosome 11 (64,223,799 to 64,226,823, reverse strand). Ensembl gene ENSG00000149743.
Subcellular location (Human Protein Atlas): Mitochondria
Gene Ontology:
Molecular function: tRNA 2'-phosphotransferase activity; transferase activity
Biological process: tRNA splicing, via endonucleolytic cleavage and ligation
Genetic constraint (gnomAD): Loss-of-function variants: 23 observed, 26.52 expected, observed/expected ratio (o/e) 0.87, 90% interval 0.62 to 1.23. The upper end of that interval is the gene's LOEUF score, 1.23, which puts it in group 5 of 6, group 1 being the genes least tolerant of losing a copy. Missense variants: 307 observed, 308.35 expected, observed/expected ratio (o/e) 1, 90% interval 0.91 to 1.09. Synonymous variants: 137 observed, 128.46 expected, observed/expected ratio (o/e) 1.07, 90% interval 0.93 to 1.23.
Homologues: Orthologues: macaque TRPT1 (86% identical), pig TRPT1 (85% identical), chimpanzee TRPT1 (85% identical), rabbit TRPT1 (84% identical), guinea pig TRPT1 (83% identical), mouse Trpt1 (82% identical), rat Trpt1 (81% identical), dog TRPT1 (73% identical), tropical clawed frog trpt1 (53% identical), zebrafish trpt1 (48% identical), Drosophila melanogaster Tpt (31% identical).